RECK (reversion inducing cysteine rich protein with kazal motifs)
Diseases named in the same sentence as RECK in open-access papers (continued):
Sharing a sentence is not in itself a finding about the gene and the disease.
tumor (continued). "For example, miR-21 has been reported to downregulate PTEN, PDCD4, and RECK—tumor suppressors that are essential for maintaining cellular homeostasis—thereby potentially promoting abnormal cell proliferation and migration in non-target tissues." (PMID 41437101, 2025). "This evidence supports a role for RECK in the regulation in vivo of MMPs which are known to be involved in cancer progression and implicate RECK downregulation in tumor angiogenesis." (PMID 38612895, 2024). "They show that RECK is repressed in tumor tissue compared to matched background liver controls, and the abundance of miR-21 and high mobility group box-1 is inversely correlated with levels of RECK." (PMID 38612895, 2024). "In exploring miR-21 target genes, we focused on the RECK gene, a tumor suppressor gene whose protein product functions as a negative regulator for MMPs." (PMID 38612895, 2024). "First, pancreatic RECK inactivation markedly increased both spontaneous development of PDAC and its metastasis to the liver, providing the first direct evidence to our knowledge that RECK is a bona fide tumor suppressor." (PMID 37712427, 2023). "In particular, RECK has been implicated in the attenuation of tumor metastasis by negatively regulating MMP levels and this role of RECK was also evaluated in CCA." (PMID 38139236, 2023). "According to the findings above, RECK inhibited tumor proliferation, migration, and invasion by inactivating the MAPK/ERK signaling pathway." (PMID 37904179, 2023). "The expression of RECK declined in the tumor group compared to the normal group (p = 0.0040 < 0.05)." (PMID 37255541, 2023). "Rescue experiments revealed that the molecular mechanism by which RECK in inhibited tumor proliferation, migration, and invasion was mediated by ERK/MAPK signaling in AGS and HGC-27 cells." (PMID 37904179, 2023). "In humans, RECK is widely expressed in normal tissues and is reduced in the tissues of many tumor types." (PMID 37712427, 2023). "In summary, our study revealed that RECK was a favorable prognostic factor and acted as a tumor suppressor of tumor cell proliferation, migration and invasion mediated by inactivation of MAPK/ERK signaling." (PMID 37904179, 2023). "TMPRSS4 overexpression suppressed RECK expression together with increased tumor angiogenesis, through activating the ERK1/2 pathway as well as promoted metastasis of HCC cells in vivo." (PMID 38139236, 2023). "RECK is a recently explored tumor-inhibitor gene and is known as a matrix metalloproteinase inhibitor, in turn, decreasing the tumor invasion and angiogenesis." (PMID 36662090, 2023). "A previous study indicated that high RECK levels in resected PDAC tissues correlated with better prognoses of patients, implying that RECK plays a tumor-suppressive role in PDAC." (PMID 37712427, 2023). "Here, we demonstrated that increasing RECK expression is distinctly associated with the ESTIMATES score, especially CD4+ and CD8+ T infiltrating cells in the tumor microenvironment of GC." (PMID 37904179, 2023). "Third, the correlation of RECK with tumor immunity status requires additional experimental verification." (PMID 37904179, 2023). "Based on the findings above, we investigated the potential linkages between RECK expression, tumor immunity, and metastasis since CSCs were closely related to tumor immunity status and metastasis." (PMID 37904179, 2023). "Meanwhile, mechanistic investigations demonstrated that RECK remarkably suppressed tumor growth and the EMT process mediated by the inactivation of ERK/MAPK signaling." (PMID 37904179, 2023). "Mechanistically, the antitumour effects of RECK on hampering tumor cell growth, migration, and invasion were mediated by the ERK/MAPK signaling pathway." (PMID 37904179, 2023). "The overexpression of GAS5 can promote the reduction in miR-21 expression, increase the levels of RECK, and increase tumor cell apoptosis after radiotherapy." (PMID 35241975, 2022).
tumor (continued). "The reversion-inducing cysteine-rich protein with kazal motifs (RECK), initially considered a tumor suppressor gene, has been demonstrated to inhibit tumor invasion and metastasis by negatively regulating MMP2 and MMP9." (PMID 35562926, 2022). "In mouse models, forced expression of RECK in tumor xenografts results in suppression of tumor angiogenesis, invasion, and metastasis." (PMID 35149728, 2022). "On the other hand, forced RECK expression in cancer cells was found to result in suppression of tumor angiogenesis and metastasis in a mouse xenograft model." (PMID 35149728, 2022). "Sp1 is overexpressed in most tumours and can inhibit RECK transcription by binding to its promoter region." (PMID 35892136, 2022). "Our screen for chemicals capable of inducing RECK expression and flat reversion in tumor cells led to the identification of a metastasis suppressing drug, DSK638." (PMID 35149728, 2022). "RECK is down-regulated in many tumors, and the mechanism of this down-regulation is multifactorial and tumor-specific." (PMID 34876128, 2021). "RECK, a tumor suppressor gene, is critical for the regulation of the migratory and invasive capacities of tumor cells." (PMID 34876128, 2021). "Here, we showed that RECK+ tumors presented reduced tumor and endothelial cell populations and increased inflammatory infiltrate." (PMID 34066355, 2021). "Here, we performed a series of experiments in order to determine the impact of RECK expression in tumor growth kinetics in vivo." (PMID 34066355, 2021). "First, we investigated the mRNA levels of RECK in human tissues using the GTEx database and in tumor cell lines from CCLE database." (PMID 34093791, 2021). "Across all tumor categories, preserving RECK expression was shown to inhibit MMP2 and MMP9 activity, and improve prognosis by decreasing invasion and metastasis." (PMID 34745017, 2021). "Reversion-inducing cysteine-rich protein with Kazal motifs (RECK) is a glycoprotein located on the cell membrane, and its expression is reduced in tumor cells." (PMID 34876128, 2021). "We observed that tumors established from SiHa RECK+ or SW756 RECK+ cells exhibited delayed tumor detection compared to those obtained from control cells." (PMID 34066355, 2021). "RECK is a tumor suppressor and hypoxia significantly downregulates RECK mRNA and protein expression, while the effect is abolished by knockdown HIF‐1α with respective siRNAs." (PMID 33463054, 2021). "RECK+ tumors displayed an increase in lymphoid-like inflammatory infiltrating cells, reduced number and viability of tumor and endothelial cells and lower collagenase activity." (PMID 34066355, 2021). "In the minority of tumor samples where RECK levels are normal or elevated, there is generally a reduction in local invasion, metastasis and an improved prognosis." (PMID 34093791, 2021). "RECK affects not only tumor progression but also tissue architecture remodelling in embryonic development." (PMID 33987019, 2021). "The absolute number of inflammatory cells per 100,000 tumor cells was also increased in RECK+ tumors." (PMID 34066355, 2021). "Reversion-inducing cysteine-rich protein with kazal motifs (RECK), which is a tumor suppressor, regulates matrix metalloproteinases (MMPs) by breaking down the extracellular matrix (ECM)." (PMID 33987019, 2021). "When RECK inhibits MMPs, the basement membrane remains intact and inhibits tumor angiogenesis to prevent blood vessels from supplying to tumor cells." (PMID 33987019, 2021). "RECK was first described, in a murine fibroblast cell, as a tumor suppressor acting in the reversion of the malignant phenotype induced by the Ras oncogene." (PMID 34205376, 2021). "For example, RECK/MMP-mediated ECM remodeling plays a role not only in tumor cell spread, but also leukocyte infiltration into tissues." (PMID 34745017, 2021). "On the other hand, SiHa RECK+ and SW756 RECK+ tumors exhibited a lower proportion of tumor cells (49.7 ± 11.5% and 37.6 ± 12.7%, respectively)." (PMID 34066355, 2021).
tumor (continued). "RECK negatively regulates the activity of MMPs and reduces cancer cell invasion, metastasis, and tumor angiogenesis." (PMID 32349289, 2020). "Expression levels of MAGI2-AS3 and RECK mRNA in two types of tissues (non-tumor and NCSLC) were measured by qPCR." (PMID 32138716, 2020). "Consistently, restored expression of RECK in tumour cells suppresses angiogenesis, invasion and metastasis in animal models, and the level of residual RECK expression in tumour tissues correlates with better prognosis." (PMID 32286475, 2020). "Reversion-inducing cysteine-rich protein with Kazal motifs (RECK), which is essential for embryogenesis and tumour suppression, has been reported to inhibit MMPs." (PMID 32286475, 2020). "All these findings suggest that RECK has a potential therapeutic value as a tumour suppressor for the treatment of malignant conditions." (PMID 32286475, 2020). "The mRNAs HOXA5, MTSS1, PTEN, and RECK are reported to have important tumor-suppressive roles in OC, though their role in HGSC is not specifically shown." (PMID 31842477, 2019). "RECK negatively regulates some matrix metalloproteinases which are known to facilitate tumor invasion and metastasis." (PMID 31338326, 2019). "In summary, we identified a tumor suppressing role of GAS5 in HCC invasion by positively regulating RECK expression in a ceRNA manner." (PMID 30733959, 2019). "Compelling evidence from experimental studies as well as analyses of clinical specimens implicate RECK in tumor suppression." (PMID 30287421, 2018). "Previous studies have reported that RECK is newly found as a transformation-suppressor gene, which can inhibit the process of tumor metastasis and invasion through regulating the expression of MMPs and Cadherin families." (PMID 28208619, 2017). "RECK expression is frequently silenced in aggressive tumor cells by HDAC, and suppressed by HER-2/neu and RAS also through a histone deacetylation mechanism." (PMID 28134767, 2017). "To determine the time-point at which RECK is inactivated during the stepwise evolution of HBP carcinomas, we first sought to explore RECK expression during the sequential progression of HBP tumours from normal buccal pouch epithelium." (PMID 28515436, 2017). "HDAC inhibitors can induce ER stress, exert antitumor effects, and induce RECK expression in tumor cells; however, the role of RECK in HDAC inhibitor-induced ER stress is unclear." (PMID 28134767, 2017). "Overexpression of RECK has been demonstrated to inhibit tumour development and progression by downregulating the expression of MMPs and abrogating vascular endothelial growth factor (VEGF) and Notch signalling." (PMID 28515436, 2017). "RECK downregulation is reported to stimulate invasion and angiogenesis in several tumours including liver, lung, breast, prostate, oral and digestive tract cancers." (PMID 28515436, 2017). "Taken together, these findings provide compelling evidence that RECK is a keystone protein that regulates mediators of tumour invasion and angiogenesis." (PMID 28515436, 2017). "RECK is a tumor and metastasis suppressor gene and is critical for regulating tumor cell invasiveness and metastasis." (PMID 28134767, 2017). "Restoration of RECK expression in tumor cells suppresses the angiogenesis, invasion, and metastasis of tumors." (PMID 28134767, 2017). "Several synthetic and natural agents upregulate RECK through different strategies thereby blocking tumour progression." (PMID 28515436, 2017). "We also report the chemotherapeutic potential of nimbolide based on upregulation of RECK as well as modulation of the expression of key molecules involved in tumour invasion and angiogenesis." (PMID 28515436, 2017). "RECK control by miR-21 overexpression results in invasion and tumour recurrence in patients following surgical treatment of prostate cancer." (PMID 28515436, 2017). "Forced RECK expression in cancer cells results in suppression of tumor angiogenesis, invasion, and metastasis in xenograft models." (PMID 27058625, 2016).
tumor (continued). "First, comparison between matched pairs of normal and tumor tissues (n=13) indicated significant downregulation of RECK mRNA (P=0.001) and prevalence of RECK CpG methylation, both RPM and RIM, in tumor tissues (bar 2, 4)." (PMID 27058625, 2016). "RECK functions as a metastasis suppressor by membrane-bound inhibiting MMPs, which play an important role in extracellular matrix remodeling during tumor progression." (PMID 26969625, 2016). "A positive correlation has been observed between the abundance of RECK expression in tumor samples and a more favorable prognosis for patients with several types of tumors." (PMID 26431549, 2015). "Canonical RECK over-expression in different tumor cell lines, including the GBM T98G cells, is extensively described in the literature and shown to inhibit their invasive capacity." (PMID 26431549, 2015). "Recent evidence indicates that several oncogenic microRNAs target RECK mRNA20, 22, 23, 24, 25, 26, strengthening the notion that RECK is a tumor suppressor that is downregulated via various mechanisms during carcinogenesis." (PMID 26658478, 2015). "We demonstrate, for the first time, TMPRSS4 remarkably suppresses the expression of RECK, an inhibitor of angiogenesis, drastically induces tumor angiogenesis." (PMID 26190376, 2015). "The reversion-inducing cysteine-rich protein with Kazal motifs (RECK) gene is a membrane-anchored glycoprotein that negatively regulates matrix metalloproteinases (MMPs) and inhibits tumor metastasis and angiogenesis." (PMID 25885317, 2015). "RECK is expressed in various of human tissues and untransformed cells, and it is undetectable in tumor-derived cell lines and oncogenically transformed cells." (PMID 26190376, 2015). "For a better understanding of the role of RECK and EVI5 in miR-135b-mediated tumor invasion, we first examined the expression and function of RECK and EVI5 in HCC." (PMID 25537516, 2015). "RECK suppresses tumor invasion by negatively regulating at least three members of the matrix metalloproteinase family: MMP-9, MMP-2, and MT1-MMP." (PMID 26431549, 2015). "Of particular interest is GAS1, an apoptosis inducer, which is inactivated in a wide range of different cancers, as well as RECK, a tumor and metastasis suppressor." (PMID 25886003, 2015). "More over, we found that overexpression of TMPRSS4 also significantly suppressed the expression of RECK, together with increased tumor angiogenesis, through activating ERK1/2 pathway." (PMID 26190376, 2015). "RECK, a tumor suppressor downregulated in a wide variety of cancers, encodes a membrane-anchored matrix-metalloproteinase-regulator." (PMID 26658478, 2015). "Patients with high RECK protein levels in tumor tissues usually have improved survival outcomes, with tumors being less invasive, as demonstrated in clinical investigations." (PMID 24765174, 2014). "RECK is thought to be a tumor invasion and metastasis suppressor gene, and was also found to inhibit tumor cell growth and motility in both lung and bladder cancer." (PMID 25084400, 2014). "RECK acts as a negative regulator of tumor invasion and metastasis by suppressing MMP-2 and MMP-9 activities." (PMID 25116803, 2014). "The tumor suppressor RECK is able to suppress tumor angiogenesis, invasion and metastasis, inhibiting MMP-2 and MMP-9." (PMID 25909813, 2014). "Otherwise, preservation of RECK expression in some neoplasms correlates with a relatively low microvascular density as well as with a better prognosis, due to a decreased tendency to metastatic invasion." (PMID 25432084, 2014). "Decreased RECK expression was confirmed by Western blotting in tissue of eight normal/tumor matches of patients after radical nephrectomy, whereas the EMMPRIN pattern appeared to be heterogeneous." (PMID 24131772, 2013).
tumor (continued). "miR-21 also targets RECK (reversion-inducing-cysteine-rich protein with kazal motifs), a tumor and metastasis suppressor that inhibits tumor metastasis and angiogenesis through modulation of matrix metalloproteinases." (PMID 23629677, 2013). "Colony formation assays and in vivo tumor xenograft experiments suggested that the suppression of RECK by hypoxic stress is required to transform normal cells to tumor-like cells by enhancing their proliferative abilities." (PMID 24376819, 2013). "RECK is known to be a strong suppressor of tumour invasion and metastasis, regulating metalloproteinases which are involved in cancer progression." (PMID 23382691, 2013). "Reversion-inducing cysteine-rich protein with Kazal motifs (RECK) is a tumor suppressing, membrane-anchored glycoprotein that contains multiple epidermal growth factor-(EGF)-like repeats and multiple serine protease inhibitor-like domains." (PMID 24376819, 2013). "Comparison of tumor and adjacent normal tissue pairs revealed a significant decrease of RECK expression in the tumor areas (Wilcoxon matched-pairs signed rank test, P < 0.001), whereas expression of EMMPRIN remained unchanged (P = 0.991)." (PMID 24131772, 2013). "RECK is a tumor suppressor gene that negatively regulates MMPs and inhibits tumor invasion, angiogenesis, and metastasis." (PMID 23771133, 2013). "RECK staining was mainly observed in the cytoplasm and plasma membrane of the tumor cells, often in a granular pattern." (PMID 23833658, 2013). "In tumor tissues, RECK expression levels are significantly reduced, and the downregulation of RECK has been implicated in tumors that are more aggressive with a poor prognosis." (PMID 23833658, 2013). "RECK staining was found in tumor-surrounding normal tissue in the medulla as well as in the renal cortex." (PMID 24131772, 2013). "Inhibition of miR-21 leads to increasing levels of RECK, a membrane-anchored glycoprotein that inhibits tumor cell invasion by regulating MMP-2, MMP-9 and MT1-MMP." (PMID 22642976, 2012). "A previous study showed high RECK mRNA expression in HCC tumor tissues from patients with better survival and less invasive clinicopathologic features." (PMID 22428065, 2012). "Previous research confirms the relationships of RECK expression and gene status with tumor metastasis." (PMID 22428065, 2012). "In PCa cell line DU-145 miR-21 showed that directly inhibits RECK, a tumor suppressor gene that is involved in the control of MMP9." (PMID 22642976, 2012). "RECK gene is expressed in various normal organs and has been found to be important in suppressing tumor invasion, metastasis and angiogenesis." (PMID 22438955, 2012). "RECK-expressing tumors show a significant reduction in microvessel density and branching, and result in tumor tissue death in mice." (PMID 22428065, 2012). "Forced expression of RECK in cancer cells suppresses tumor angiogenesis, invasion, and metastasis in xenograft models." (PMID 21304177, 2010). "Clinical studies also indicate that the levels of residual RECK expression in resected tumor tissues positively correlate with survival of the patients." (PMID 21304177, 2010). "Such down-regulation is probably essential for carcinogenesis, since forced expression of RECK in cancer cells suppresses tumor angiogenesis, invasion, and metastasis as assessed by xenograft experiments in nude mice." (PMID 21304177, 2010). "RECK is down-regulated in a wide variety of tumors and in the cells transformation by various oncogenes; forced expression of RECK in tumor cells results in suppression of tumor proliferation, angiogenesis, invasion, and metastasis." (PMID 21304177, 2010). "RECK suppresses tumor angiogenesis, invasion, and metastasis when artificially expressed in tumor cells." (PMID 20691046, 2010). "Again, it seems difficult to fully explain the effects of RECK on tumor angiogenesis by enhanced Notch signaling." (PMID 20691046, 2010).